AFP (alpha fetoprotein)
Diseases named in the same sentence as AFP in open-access papers (continued):
Sharing a sentence is not in itself a finding about the gene and the disease.
liver cancer (continued). "Moreover, AFP and HSA exhibited numerous similarities, such as overall conformation resemblances and multiple high-affinity FA binding sites, which enabled AFP to possess potential as a drug delivery system that holds great promise for the treatment of certain cancers (e.g., liver cancer)." (PMID 38678117, 2024). "AFP, a common liver cancer diagnostic indicator, is not sufficient by itself to determine whether a patient is diagnosed, but needs to be combined with Computed Tomography and other techniques." (PMID 36990999, 2023). "Thus, AFP is widely used for the diagnosis and monitoring of liver cancers." (PMID 37241360, 2023). "Furthermore, hematoxylin and eosin (H&E) and immunofluorescence staining showed that original HCC tissues expressed alpha‐fetoprotein (AFP, liver cancer marker) and vimentin (VIM, stromal cell marker) and exhibited high expression of Ki67 (cell proliferation marker)." (PMID 37485650, 2023). "The tumor markers CEA, AFP, CA199, CA125 and CA724 are widely used in the auxiliary diagnosis of digestive system tumors; among them, AFP has been widely recognized as a specific diagnostic marker for liver cancer, and CEA has better diagnostic value in the diagnosis of digestive system tumors." (PMID 36920593, 2023). "Thus, a high serum AFP level may be an alternative parameter of a good predictor of postoperative liver cancer recurrence." (PMID 37519810, 2023). "However, there are similar problems with AFP in the diagnosis of liver cancer." (PMID 37546394, 2023). "However, AFP is a specific tumor marker of liver cancer, and its serum expression level in GC patients may be significantly lower than that in liver cancer patients." (PMID 35710379, 2022). "Furthermore, HBV-related liver cancer indicates higher AFP levels." (PMID 35306637, 2022). "This indicates that FCN2 has certain clinical importance, whether from the high and low FCN2 expression groups (median) or the expression analysis of normal liver tissue and different liver cancer subgroups, and could be a complementary gene for AFP detection in liver cancer." (PMID 36425563, 2022). "Although a negative serum AFP may be associated with favorable liver cancer outcomes, it results in a miss diagnosis of liver cancer in general." (PMID 35461226, 2022). "Previous studies have evidenced that the transfection of Fth reporter gene with alpha-fetoprotein promoter (AFP-Fth) could induce a high expression level of ferritin only in the liver cancer cells, which therefore shows a potential ability in the diagnosis of HCC via MRI technique in vivo." (PMID 33731140, 2021). "Furthermore, even though much progress has been achieved, a current screening methodology, such as computed tomography, and a biomarker, such as alpha-fetoprotein (AFP), exhibit low sensitivity and specificity for detecting early liver cancers that can hardly be acceptable in a clinical field." (PMID 34208132, 2021). "Besides, more than 70% liver cancer patients show positive AFP." (PMID 34306031, 2021). "Therefore, the down-regulation of circulating or cytoplasmic AFP expression may be helpful in the treatment of liver cancer." (PMID 33765973, 2021). "For example, multiple or single tumor nodules determine the prognosis of liver cancer patients treated differently, while a high level of AFP may affect the biological behavior of liver cancer, such as invasion, postoperative metastasis and recurrence, and prognosis." (PMID 32070301, 2020). "We thus asked whether AFP activation is related to the molecular classification of liver cancer." (PMID 31897235, 2020). "However, AFP is elevated in almost all liver cancer patients." (PMID 32774373, 2020). "However, ~300 MOI of OV-EBFP were required to efficiently kill the mouse liver-cancer Hepa1-6 cells, which may be due to the low AFP gene expression level and low viral replication capability in Hepa1-6 cells." (PMID 31641136, 2019). "Therefore, AFP has become a new target for the treatment of liver cancer." (PMID 29805966, 2018).
liver cancer (continued). "Although the immunogenicity of AFP is weak and it could induce the immune escapes through inhibiting the function of dendritic cells, natural killer cells, and T lymphocytes, AFP has attracted more attention in liver cancer immunotherapy." (PMID 29805966, 2018). "Thus, AFP plays an important role in the development and progression of liver cancer." (PMID 29805966, 2018). "The diagnosis of liver cancer is generally performed by imaging techniques, such as ultrasonography, computed tomography and magnetic resonance tomography, in combination with the dosage of plasmatic alpha-fetoprotein (AFP) and histological analysis of tissue biopsies." (PMID 29597259, 2018). "In addition, the AFP (a liver cancer marker) was expressed in the liver tumor tissue." (PMID 27833137, 2016). "Hence, regulation of PI3K/AKT signaling pathway may be the possible molecular mechanism that mediate AFP-induced malignant progression of liver cancer, such as tumorigenesis, growth, migration and invasion." (PMID 27835609, 2016). "AFP-induced over-expression of Fas on the surface of lymphocytes, together with simultaneous over-secreted FasL from tumor cells, could be one of reasons to accelerate the death of lymphocytes and facilitate the immune escape of liver cancer." (PMID 16080799, 2005). "There were significant differences between the two groups in sex, history of liver cancer treatment, HCV‐RNA levels, serum albumin levels, AST levels, γ‐GTP levels, creatinine, eGFR, prothrombin activity, platelet counts, and AFP levels." (PMID 41573355, 2026). "An easy-to-engineer nanobiosensor electrode platform was developed using commercial screen-printed electrode (SPE) as the sensor substrate, enabling cost-effective detection of alpha-fetoprotein (AFP), a clinically important biomarker of liver cancer." (PMID 42200437, 2026). "Additional relevant biomarkers such as Mesothelin, Endoglin, AFP, and CEA contribute to classification, with color-coded SHAP values showing their differential impact between Ovarian and Liver cancer." (PMID 40217526, 2025). "For instance, AFP, a crucial HCC tumor marker, is incorporated into many liver cancer prognostic models." (PMID 40808940, 2025). "The AUC of TRIM22 diagnosis of liver cancer is 0.924, which can distinguish liver cirrhosis patients with normal HCC and normal AFP." (PMID 41472269, 2025). "Histologically, the tumor showed hepatoid differentiation with positive immunohistochemical staining for AFP, HepPar-1, and GPC3, indicating a tumor profile highly reminiscent of liver cancer." (PMID 40430002, 2025). "The efficacy of these AFP-CAR T cells was evaluated in animal models, demonstrating their ability to suppress AFP-positive liver cancer cells." (PMID 40430002, 2025). "Further subgroup analyses were conducted based on geographic region, etiology, performance status (PS), presence of macrovascular invasion (MVI) and/or extra hepatic spread (EHS), Barcelona Clinic Liver Cancer (BCLC) stage, and α-Fetoprotein (AFP) levels." (PMID 41451207, 2025). "These include hematological markers such as alpha-fetoprotein (AFP), the albumin-bilirubin (ALBI) ratio, the model for end-stage liver disease (MELD) score, the Barcelona Clinic Liver Cancer (BCLC) staging system, and the Child-Pugh score." (PMID 40308633, 2025). "Compared to traditional markers such as alpha-fetoprotein (AFP), LG3BP and PIGR show higher sensitivity and specificity in early diagnosis of liver cancer." (PMID 40433362, 2025). "NR, Not Reached; HR, Hazard Ratio; CI, confidence interval; HBV, hepatitis B virus; HCV, hepatitis C virus; BCLC, Barcelona Clinic Liver Cancer; AFP, alpha fetoprotein." (PMID 41049859, 2025). "To confirm the hepatic origin of these metastatic lesions, we conducted immunohistochemical staining for liver cancer-related markers (ALB and AFP) with human-specific antigens (human GAPDH and human nuclear antigen) in the metastatic lesions." (PMID 40852642, 2025).
liver cancer (continued). "The aim of this study was to find the optimal patterns of serum AFP, AFP-L3% and PIVKA-II for the diagnosis of liver cancers to provide clearer guidance on the selection of hematological diagnostic methods for liver cancers in clinical practice." (PMID 40708828, 2025). "The results of this study showed that intact capsule, tumor > 5 cm, AFP, CAR, CD147, and IL-6 were all independent factors affecting the invasion and metastasis of primary liver cancer." (PMID 40919145, 2025). "Alpha-fetoprotein (AFP), a protein produced by hepatocytes, is also the most widely detected serum biomarker of liver cancer, and excessive AFP is considered to be related to the biological characteristics and burden of more aggressive tumors." (PMID 40919145, 2025). "Logistic multivariate analysis showed that intact capsule, tumor > 5 cm, AFP, CAR, CD147, and IL-6 were all independent factors affecting the invasion and metastasis of primary liver cancer (p < 0.05)." (PMID 40919145, 2025). "Traditional HCC staging, such as Barcelona clinic liver cancer (BCLC) stage and American Joint Committee on Cancer (AJCC) TNM stage, and serum alpha-fetoprotein (AFP) are currently being widely used to guide clinical practice." (PMID 40535812, 2025). "Thus, for the detection of serum AFP, AFP-L3% and PIVKA-II, the GALAD, ASAP, GALAD-C and C-GALAD diagnostic models are preferentially recommended because they showed the highest efficacy (AUC) in the diagnosis of HCC, liver cancers (HCC + CCA), and early liver cancers." (PMID 40708828, 2025). "When incorporated into a clinical prognostic model that includes age, alpha-fetoprotein (AFP), the CHILD–Pugh score, and the Barcelona Clinic Liver Cancer (BCLC) staging system, CNP had a significant incremental value in predicting OS (IDI 1.3%, p = 0.04)." (PMID 40131621, 2025). "This study explored the optimal patterns of serum AFP, AFP-L3% and PIVKA-II for the diagnosis of liver cancers." (PMID 40708828, 2025). "Notably, these characteristics of AFP are not restricted to liver cancer but are also closely associated with poor prognosis, inadequate treatment response, and increased metastatic potential in various cancers, including germ cell tumors, colorectal cancer, and gastric cancer." (PMID 40430002, 2025). "The tumor hepatocytes expressed high levels of ALB, AFP, and STAT3, with the later two genes known to be altered in liver cancer and fibrosis, respectively." (PMID 40766612, 2025). "Variables examined were: Barcelona Clinic Liver Cancer (BCLC) stage, Child-Pugh class, albumin-bilirubin (ALBI) grade, alpha fetoprotein (AFP) level, microvascular invasion (MVI), and distant metastases." (PMID 39996905, 2025). "The patient was also found to have high AFP and PIVKA at the time of diagnosis of primary liver cancer." (PMID 38430249, 2024). "Conventional imaging studies and the measurement of tumor markers such as AFP (Alpha-fetoprotein), CA125 (Cancer Antigen 125), and CA19-9 remain the mainstays of liver cancer diagnosis." (PMID 39033781, 2024). "Alpha-fetoprotein (AFP), a serum glycoprotein, is expressed during embryonic development and the pathogenesis of liver cancer." (PMID 38678117, 2024). "A series of Japanese studies from a liver cancer center showed that 19% of patients with ICC had serum AFP levels > 20 ng/mL, 10.3% of them had >200 ng/mL, while serum AFP levels > 1000 ng/mL was recorded in 6.3% of the cases." (PMID 39064538, 2024). "Furthermore, we also observed that higher ADAM10 expression was often found in liver cancer patients with the following characteristics: age equal to or less than 65 years, larger tumors, G3 and G4 stage patients, higher AFP levels, microsatellite lesions, TACE sensitivity, and sorafenib resistance." (PMID 39346916, 2024). "The multivariate analysis revealed older age and higher ALBI score in Barcelona Clinic Liver Cancer (BCLC) 0/A stage, AFP of >20 ng/mL, and higher ALBI score in BCLC B stage as independent prognosis factors." (PMID 38452155, 2024).
liver cancer (continued). "Alpha-fetoprotein (AFP), Osteopontin (OPN) and Glypican-3 (GPC-3) are commonly used as tumor markers for primary liver cancer." (PMID 37575092, 2023). "While AFP is the gold standard, it has limitations in detecting different grades and stages of HCC and accurately differentiating between primary liver cancer types." (PMID 36980321, 2023). "A clinical study found that patients with advanced liver cancer benefited from ICT therapy, which promoted apoptosis in HCC by inhibiting alpha-fetoprotein (AFP) expression." (PMID 36843953, 2023). "The designed QCM test system can easily and quickly detect AFP concentrations up to 760 ng/mL, indicating that the developed QCM assay is likely to lead to an alternative approach in large-scale screening for liver cancer in the near future." (PMID 37175021, 2023). "The Barcelona Clinic Liver Cancer (BCLC) staging system classifies HCC according to patient characteristics (performance status, PS) and prognosis (Child-Pugh, alpha-fetoprotein [AFP] level, MELD, ALBI score, tumour size and liver function)." (PMID 37692859, 2023). "Currently, alpha-fetoprotein (AFP) is one of the most common and important tumor biomarkers for liver cancer." (PMID 37836778, 2023). "Alpha-fetoprotein (AFP), Osteopontin (OPN), Glypican-3 (GPC-3) and Arginase-1 (Arg-1) are common primary liver cancer related biomarkers." (PMID 37575092, 2023). "Here, a systematic review and meta-analysis was performed to evaluate the significance of the combined use of AFP and CRP values in predicting the clinical outcomes of liver cancer patients treated with immunotherapy." (PMID 36915049, 2023). "Further, 60 (63.8%) were of Barcelona clinical liver cancer (BCLC) stage C and 19 cases (20.2%) were of BCLC stage B; 56 (59.6%) patients had an initial AFP > 400 ng/mL." (PMID 36793614, 2023). "This is a promising sign of our ongoing work, utilizing DEXs to bind with short peptides of liver cancer-specific AFP and GPC3 that can more specifically activate T lymphocytes for prevention or targeted therapy of liver cancer." (PMID 37631284, 2023). "Eight potential prognostic variables for OS were selected based on univariate Cox analysis, namely Child‒Pugh grade, Barcelona Clinic Liver Cancer (BCLC) stage, ECOG PS, a-fetoprotein (AFP) level, involved organs, TBS, MVI, and combination with local therapy." (PMID 36753026, 2023). "When elevated AFP is seen and mass is found in the liver on CT images, we need to be cautious in differentiating HAS from primary liver cancer." (PMID 36816961, 2023). "AFP, a serum marker clinically used for PLC diagnosis and highly expressed in patients with liver cancer, exhibited a significant reduction following SS-b2 treatment." (PMID 37893233, 2023). "In order to observe the effect of AFP on macrophages phagocytizing polystyrene latex beads or HCC cells, tumor-derived AFP(tAFP) from liver cancer loading patient was purified, and healthy human(donor) monocytes were collected." (PMID 36911723, 2023). "Although serum AFP and protein induced by PIVKA‐II are clinically approved biomarkers for monitoring the progression of liver cancer, their usefulness is hindered by low sensitivity." (PMID 36587393, 2023). "Furthermore, PIVKA-II shows a significant diagnostic value for AFP-negative liver cancer." (PMID 37189543, 2023). "This study aims to analyze the application value of contrast-enhanced ultrasound and enhanced CT and tumor markers AFP and CA199 in the clinical diagnosis of liver cancer." (PMID 35237392, 2022). "Namely, in predicting NAFLD-related liver cancer, kappa coefficients were 0.528, 0.389, and 0.024 in TERT C228T, PIVKAII positivity, and AFP positivity, respectively." (PMID 35306637, 2022). "Our recent report highlighted the better performance of TERT C228T in serum cfDNA than AFP and PIVKAII in the early diagnosis of primary liver cancer in patients with non-alcoholic fatty live disease (NAFLD)." (PMID 35306637, 2022).
liver cancer (continued). "Although the levels of AFP and CA199 have also increased, their levels are much lower than those of the liver cancer group." (PMID 35237392, 2022). "The present study showed that pinealectomy or exposure to constant light resulted in a significant increase in AFP, CD44, TGFβ-1, and VEGF levels indicating early development and progression of hepatic cancer cells." (PMID 35419691, 2022). "Cox univariate analysis found that ZNF334, AFP, AST, and MVI were related to overall survival (OS) in patients with liver cancer; ZNF334, AFP, MVI, and portal vein tumor thrombus were related to postoperative relapse-free survival (RFS)." (PMID 35534462, 2022). "ECOG PS, Eastern Cooperative Oncology Group performance status; HBV, hepatitis B virus; HCV, hepatitis C virus; BCLC, Barcelona Clinic Liver Cancer; AFP, alpha-fetoprotein; PIVKA-II, protein induced by vitamin K absence or antagonist-II." (PMID 35406518, 2022). "We observed that metabolites and lipids are closely related to AFP, maximum tumor diameter, tumor-node-metastasis (TNM) stage and the Barcelona Clinic Liver Cancer (BCLC) stage, which are known as the prognostic indicators in HCC." (PMID 35406630, 2022). "This study aims to explore the application value of contrast-enhanced ultrasound and enhanced CT combined with tumor markers alpha-fetoprotein (AFP) and carbohydrate antigen 199 (CA199) in the diagnosis of liver cancer." (PMID 35237392, 2022). "Nowadays, AFP, AFP-L3, and DCP have become the most widely used serum biomarkers for early diagnosis of liver cancer." (PMID 36110223, 2022). "The ROC curve showed that the sensitivity, accuracy, and negative prediction rate of contrast-enhanced ultrasound and enhanced CT combined with tumor markers AFP and CA199 in the diagnosis of liver cancer were significantly higher than that of a single test." (PMID 35237392, 2022). "The proliferation of liver cancer cells stimulates the expression of AFP and CA199 in serum, leading to a significant increase in the levels of AFP and CA199." (PMID 35237392, 2022). "We also anticipate further studies to examine the therapeutic effects of gemcitabine, alone or in combination, on AFP-positive HCC patients, with the aim of improving the outcomes of liver cancer treatment." (PMID 35127582, 2022). "ROC curve of AFP and CA199 combined with contrast-enhanced ultrasound and enhanced CT for the diagnosis of liver cancer." (PMID 35237392, 2022). "The area under the ROC curve of AFP and CA199 combined with contrast-enhanced ultrasound and enhanced CT in the diagnosis of liver cancer is 0.962 (0.896∼0.997)." (PMID 35237392, 2022). "Alpha-fetoprotein (AFP) is a tumor marker that is often used in the diagnosis and treatment of primary liver cancer." (PMID 36389169, 2022). "The most important biomarker that has been studied is alpha-fetoprotein (AFP), which is elevated in 70% of patients with liver cancer." (PMID 35547447, 2022). "Serum levels of AFP and CA199 in the liver cancer group were significantly higher than those in the benign lesion group and the control group." (PMID 35237392, 2022). "This study showed that the levels of AFP and CA199 in the liver cancer group were higher than those in the benign liver disease group and the control group." (PMID 35237392, 2022). "Serum levels of AFP and CA199 in the liver cancer group were 191.43 ± 21.66 ng/mL and 87.57 ± 11.45 μg/mL, respectively." (PMID 35237392, 2022). "Among them, alpha-fetoprotein (AFP) and carbohydrate antigen 199 (CA199) are highly expressed in the serum of liver cancer patients." (PMID 35237392, 2022). "Note: MELD, Model for End-Stage Liver Disease; BCLC, Barcelona Clinic Liver Cancer classification; ECOG, Eastern Cooperative Oncology Group; AFP, serum alpha-fetoprotein levels; PVTT, portal vein tumor thrombus; TACE, transarterial chemoembolization." (PMID 35518553, 2022).